GLO1 (glyoxalase I)
Diseases named in the same sentence as GLO1 in open-access papers (continued):
Sharing a sentence is not in itself a finding about the gene and the disease.
cancer (continued). "The increase in GLO1 expression and activity most likely resembles a strategy adopted by aggressive cancer cells as a defense mechanism against glycation damage induced by high intracellular MG levels as a consequence of elevated glycolytic activity or under therapeutic conditions." (PMID 28549423, 2017). "In cancer cells, a better characterization of the main factors that control the level of dependence on GLO1 is needed before GLO1 inhibitors could be envisaged as promising anti-cancer drugs." (PMID 28117708, 2017). "The upregulation of GLO1 mRNA and the increase in its enzyme activity represents a defense response of tumor cells to the stress created by elevated cellular MG as a result of glycolytic adaptations to cancer (Warburg effect)." (PMID 29321821, 2017). "It is remarkable that GLO1 also plays a dual role in cancer." (PMID 28916747, 2017). "Increased GLO1 copy number and related expression has previously been considered permissive for tumour growth with high flux of glycolysis and hence flux of formation of MG and also resistance to cancer chemotherapy." (PMID 29100361, 2017). "In cancer cell lines, flavonoids act as inhibitors of glo-1." (PMID 28698611, 2017). "Importantly, knock-down of YAP using siRNA transfection reversed, at least in part, the expression of all the evaluated genes thus establishing the link between YAP target genes expression and GLO1 status in cancer cells." (PMID 27759563, 2016). "Small molecule Glo-1 inducers are in clinical development for improved metabolic, vascular and renal health and Glo-1 inhibitors in preclinical development for multidrug resistant cancer chemotherapy." (PMID 27406712, 2016). "Our results emphasize that GLO1 can be a promising target for new cancer treatment strategies." (PMID 27999356, 2016). "GLO1 upregulation has been shown to play a pivotal role in glycolytic adaptations of cancer cells." (PMID 27755556, 2016). "Glo-1 has a dual role in cancer as a tumour suppressor protein prior to tumour development and mediator of multi-drug resistance in cancer treatment, implicating dicarbonyl glycation of DNA in carcinogenesis and dicarbonyl-driven cytotoxicity in mechanism of action of anticancer drugs." (PMID 27406712, 2016). "A Glo1 inhibitor such as curcumin could be considered a drug candidate for anti-protozoan, anti-inflammatory, and anti-cancer therapy." (PMID 26694921, 2015). "Therefore, inhibition of Glo1 and/or Glo2 should result in production of toxic metabolites including aldehydes MG inside these malignant cells, which can lead to the death of cancer cells due to toxins accumulation." (PMID 23174893, 2012). "Thus, high expression of GLO1 is involved in cancer cell resistance to apoptosis induced by anti-tumor agents." (PMID 22479608, 2012). "GLO1 expression is increased in several human cancers of the colon, breast, prostate, and melanoma." (PMID 22479608, 2012). "In addition, GLO1 may also be an important therapeutic target by inhibiting GLO1 activity and inducing MG toxicity to selectively kill cancer cells, thus providing a new strategy for the treatment of drug-resistant cancers." (PMID 40352588, 2025). "Moreover, it has been shown that GLO-1 contributes to the maintenance of an immunosuppressive microenvironment through MG-H1-mediated upregulation of the immune checkpoint programmed death ligand 1 (PD-L1), thereby promoting cancer progression." (PMID 40727469, 2025). "Additionally, GLO-1 expression demonstrated strong associations with both inhibitory and stimulatory ICPs, such as CD276, VEGFA, and HMGB1, across a majority of the analyzed cancer tissues." (PMID 40727469, 2025). "Thus, comprehensive insights into the intricate interplay between aerobic glycolysis and the glyoxalase system in cancer are essentialfor the development of novel therapeutic interventions.GLO-1 is emerging as a compelling therapeutic target, particularly in glycolysis-dependent tumors." (PMID 40727469, 2025).
cancer (continued). "However, the variations observed in our study indicate that the therapeutic effectiveness of targeting GLO-1 may be dependent on the specific cancer type and its molecular context." (PMID 40727469, 2025). "GLO1 upregulation has been described in the context of metabolic and inflammatory stress in vitro and in vivo, serving as a cellular mechanism to detoxify high levels of MG, particularly in cancer, where high glycolytic rates as a result of the Warburg effect are observed." (PMID 34298821, 2021). "Indeed, the anti-cancer strategy based on Glo1 inhibition may result in potential toxic side effects related to the increasing MGO concentration, thus limiting their use in clinical practice." (PMID 33869040, 2021). "Therefore, Glo1 in cancer tissues is at a high level of expression." (PMID 31822263, 2019). "Furthermore, it remains controversial whether GLO1 in cancer acts as a tumor suppressor or oncogene." (PMID 30674353, 2019). "Because Glo1 can regulate immunity, the gene may be related to cancer." (PMID 31822263, 2019). "Moreover, it was suggested that Glo1 might represent a useful target for therapy in cancers with Glo1 amplification, such as RCa." (PMID 29385039, 2018). "In addition, GLO1 activity is reportedly elevated in many cancer types." (PMID 30559934, 2018). "Hence, we suggested that the synthesis of new molecules selectively down-regulating Glo1 expression in cancer cells might be an alternative method of therapeutic treatment for this neoplasia, in particular CCA." (PMID 29385039, 2018). "Thus, GLO1 plays a vital role in tumor initiation, malignant progression as well as treatment failure, and could serve as promising target for anti-cancer therapy." (PMID 28549423, 2017). "GLO1 gene has been reported to be overexpressed and/or amplified in several types of cancer and has been thus considered as a novel oncogene which suppression using specific inhibitors or gene silencing strategies could abolish tumor growth via toxic MG accumulation." (PMID 28117708, 2017). "Our results demonstrate that knockdown of GLO1 in the cancer cells significantly reduced tumor-associated properties such as migration and proliferation, whereas no functional alterations where found by overexpression of GLO1 in HEK 293 cells." (PMID 27999356, 2016). "Moreover, recent data indicate that GLO1 may be a valid molecular target for cancer chemotherapy, and pharmacological inhibitors of GLO1 were shown to have anticancer effects in vitro and in vivo." (PMID 27999356, 2016). "Therefore, most cancer cells show increased expression of Glo1." (PMID 18946510, 2008). "This study reveals how blocking a detox enzyme called GLO1 increases the buildup of a toxic molecule, methylglyoxal (MGO), which triggers cancer cell death by ferroptosis." (PMID 40908564, 2025). "The overexpression of Glo1 observed in HCC and other cancers is attributed to enhanced anaerobic glycolysis typical for cancer cells." (PMID 40141037, 2025). "Both GLO-1 and GLO-2 contribute to cellular redox homeostasis, but in cancer cells, an altered redox state can promote survival and resistance to therapy." (PMID 40727469, 2025). "Collectively, these findings indicate that the proteasomal degradation of GLO1, mediated by PJA1, contributes to MGO accumulation, lipid peroxidation, and ferroptosis in cancer cells." (PMID 40908564, 2025). "Glo1 inhibitors are actively being tested for cancer therapy, as many cancer types present elevated rates of glycolysis, a condition known to augment MGO formation and toxicity, where Glo1 activity improves cancer cell survival." (PMID 40867843, 2025). "Consistent with this notion, studies in mouse models have shown that knockdown of GLO-1 using shRNA constructs leads to enhanced tumor growth, further supporting a complex and context-dependent role for GLO-1 in tumorigenesis and cancer progression." (PMID 40727469, 2025).
cancer (continued). "A PPI network analysis was used to identify 17 potential targets of saponins aglycone in cancer cells, and the binding modes of saponins aglycone to four of these targets (BRD3, GLO1, CDK6, and HRAS) were confirmed using docking and MD simulations." (PMID 37996449, 2023). "On the contrary, we noted the role of GLO1, HOOK1, and GIPC2 was rarely investigated in CRC but well identified in other cancers." (PMID 36281556, 2023). "Hence, the Glo1 inducer may find application in the chemoprevention of cancer." (PMID 35269594, 2022). "Due to the possible effect exerted by MGO on cancer cells that is defined by low-dose stimulation and high-dose inhibition of tumor metastasis, it is necessary to determine the MGO concentrations when Glo1 inhibitor applied." (PMID 35898868, 2022). "Thus, the expression pattern of Glo1 may play an important role in cancer proliferation." (PMID 35898868, 2022). "GLO1 has only been characterized in a small number of HNC studies as cited; however, it is shown to have multiple roles in promoting cancer cell survival, proliferation, and is a likely target for chemotherapy based on the broader literature." (PMID 32872541, 2020). "Indeed, early studies indicate that GLO1 inhibition may show promise for chemosensitization of cancer cells, as substantiated further by the more recent identification of structure-based, non-glutathione competitive inhibitors with potent apoptogenic activity against cultured cancer cells." (PMID 32466621, 2020). "In light of the few scattered and inconsistent reports on GLO1 expression in GBM, data from The Cancer Genome Atlas (TCGA) Pan-Cancer project RNA-Seq gene expression data was interrogated." (PMID 29385725, 2018). "A potential role of GLO1 as a predictive factor for both tumour progression and response to treatment could be of particular interest, considering that GLO1 is the most frequently amplified gene in numerous human cancer cell lines, with additional GLO1 copies typically being functional." (PMID 29100361, 2017). "S-p-Bromobenzylglutathione diethyl ester was the first cell permeable Glo-1 inhibitor developed and had median growth inhibitory concentration GC50 values in the range 7–20 μM for a range of cancer cell lines." (PMID 27406712, 2016). "Glo-1 is a tumour suppressor protein and a mediator of multidrug resistance (MDR) in cancer chemotherapy." (PMID 27406712, 2016). "Consistently, in IHC analysis, a positive significant correlation was found exclusively between the scores of GLO1 and CXCL1 or CXCR2 in cancer tissues (Spearman's correlation coefficient = 0.238 and 0.293; P = 0.013 and P = 0.003, respectively)." (PMID 22479608, 2012). "In this study, we reveal a novel pathway for GLO1 degradation in ferroptosis‐sensitive cancer cells, unlike in resistant cells, via the ubiquitin‐proteasome system (UPS) driven by praja ring finger ubiquitin ligase 1 (PJA1)." (PMID 40908564, 2025). "As many cancer cells upregulate Glo1 expression to protect against MGO-induced cytotoxicity, Glo1 inhibition may represent an anticancer therapeutic strategy." (PMID 40128358, 2025). "Using the Gene Set Cancer Analysis (GSCA) database, a comprehensive resource for exploring gene-set enrichment and pathway analysis in cancer, we identified a negative correlation between GLO-1 expression and 18 distinct cancer types." (PMID 40727469, 2025). "Generally, both Glo1 and Glo2 are overexpressed in cancer cells as there is a need to rapidly metabolize the cytotoxic MGO that continuously accumulates because of the elevated glycolytic flux and metabolic activity of cancer cells." (PMID 39456676, 2024). "In particular, Glo1-driven PD-L1-mediated inhibition of cytotoxic CD8+ T cells occurred through induction of apoptosis, paralleled, as expected, by a significant reduced number of these T cells, and decreased production of specific anti-cancer cytokines." (PMID 34199263, 2021).
cancer (continued). "Identification of the IL-1β/Glo1/MG-H1/TGF-β1/FAK axis in ATC cell aggressiveness suggests that IL-1β and Glo1, which orchestrate the mechanism, may represent novel potential therapeutic targets for ATC, which remains one of the most lethal human cancers." (PMID 31174324, 2019). "Here, we demonstrated that Glo1 sustains the metastatic phenotype of PCa cells via the control of EMT, thus further extending the knowledge of the factors contributing to EMT development in cancer cells." (PMID 29504694, 2018). "This suggests that basal-like cancer cells are more highly sensitive to GLO1 inhibition than normal mammary epithelial cells." (PMID 30559934, 2018). "Higher levels of GLO1 were evident in the T3/T4 groups where the serosal surface of the gastric wall was invaded by cancer, compared to that in T1/T2 groups where no invasion was evident (P = 0.015 for qRT- PCR and P = 0.001 for IHC)." (PMID 22479608, 2012). "Expression of GLO1 was measured in cancer tissues, and compared with that in matched nontumorous gastric mucosa, using qRT–PCR (n = 89) or IHC (n = 114)." (PMID 22479608, 2012). "Our study suggests that the observed negative correlation of GLO-1 in certain cancer types may represent an additional contributing mechanism." (PMID 40727469, 2025). "The authors showed, using the Cancer Cell Line Encyclopedia (CCLE) that GLO1 mRNA expression positively correlated with the expression of spliceosome proteins (PPIL1 and CDC5L), suggesting increased GLO1 expression protects spliceosome proteins in tumour cells." (PMID 35409048, 2022). "Metformin (N,N-dimethylbiguanide), a potent anti-diabetic molecule also used in cancer treatment for its anti-tumorigenic properties, sensitizes endometrial cancer to progestin by targeting Tet methylcytosine dioxygenase 1 (TET1), which downregulates Glo1 expression." (PMID 33869040, 2021). "Finally, we examined the capacity of metformin, a widely used anti‐diabetic drug and an emerging anti‐cancer drug, especially in the field of urologic oncology, to inhibit the EMT‐based metastatic phenotype, through control of Glo1 and miR‐101 in both PCa cell lines." (PMID 29504694, 2018). "Finally, to assess the direct involvement of MG stress on the growth of GLO1 depleted HCT116 cells, we treated engrafted cancer cells with carnosine (10 mM), a MG scavenger, from the day after implantation on CAM until the end of the experiment as described under Material and Methods section." (PMID 28117708, 2017). "Cell lines with GLO1 amplification have also been shown to be more sensitive to inhibition of GLO1 by bromobenzylglutathione cyclopentyl diester (BBGC) and the gene may represent a useful target for therapy in cancers with GLO1 amplification." (PMID 23717685, 2013). "Finally, future studies could also investigate whether the Glo1/MG-H1 axis and OPN are similarly involved in ACh-driven metastasis in other cancer types and whether interventions targeting this pathway could be clinically relevant in reducing tumor progression and metastasis." (PMID 40362346, 2025).
tumor (76 papers, 2008 to 2025). "Remarkably, the majority of GLO-1-positive samples exhibited high PD-L1 expression, which was associated with enhanced tumor aggression, invasion, and expansion, leading to metastasis and an increased likelihood of recurrence." (PMID 40727469, 2025). "Beyond its association with tumorigenesis, Glo1 emerges as a key player in drug resistance, a major hurdle in effective tumor treatment." (PMID 38785990, 2024). "As Glo1 overexpression was linked to aggressive clinicopathological traits such as lymph node metastases, lymphovascular invasion, a greater tumor grade, and an advanced TNM stage, the clinical implications of Glo1 became apparent." (PMID 38785990, 2024). "Prompted by this observation, we performed RT-QPCR on GLO1-depleted tumor xenografts and validated the loss of expression of several genes composing the six main deregulated anti-oncogenic pathways and thus belonging to the 60-gene MG signature." (PMID 36998085, 2023). "In established human tumors, the increased expression and activity of GLO1 are an oncogene that is associated with tumor growth." (PMID 36612084, 2022). "Subsequent studies by this team showed that co-treatment with BBGD re-established sensitivity to antitumor drugs in Glo1-linked MDR in human tumor cell lines." (PMID 35269594, 2022). "Human tumor cell lines with increased GLO1 copy number and Glo1 expression were generally more susceptible to cytotoxic effects of silencing of Glo1 with siRNA and treatment with BBGD." (PMID 35269594, 2022). "GLO1 displayed a strong association with Gleason grade, pathological tumor stage, and early biochemical recurrence (BCR)." (PMID 34298821, 2021). "Due to the high glycolytic flux of the tumor cells, inhibition of Glo1 causes MGO burst and depletion of GSH, leading to carbonyl and oxidative stress, which eventually leads to cell dysfunction, apoptosis, and necrosis." (PMID 33396745, 2020). "We repeated the tumor allograft experiment and found that Glo1-deficient tumors exhibit evidence of increased MG-H1 adducts on proteins even at early time points." (PMID 31811141, 2019). "Specifically, we showed that high tumor MG adduct accumulation was associated with low Glo1 activity levels and aggressiveness of ATC patients." (PMID 31174324, 2019). "Overall, our data suggested that loss of tumour suppressor miR‐101 induced Glo1‐dependent EMT in DU145 and PC3 cells." (PMID 29504694, 2018). "The reversion of dicarbonyl stress onset using carnosine, a well described MG scavenger, impeded tumor development indicating that pro-tumorigenic effects associated with GLO1 inhibition were dependent upon MG glycating activity." (PMID 28117708, 2017). "We also found that in patients with midgut NET, a low GLO1 copy number was associated with increased time to tumour progression, thereby possibly representing an independent prognostic factor." (PMID 29100361, 2017). "Our data indicate that the pro-tumor effect of GLO1 silencing in CRC cells is linked with MG stress and can be blocked using a MG scavenger." (PMID 28117708, 2017). "In an animal model of hepatocellular carcinogenesis, GLO1 was found to be a tumour suppressor gene, suggesting that MGdG-linked mutations on some occasions lead to cell transformation and malignancy." (PMID 29100361, 2017). "In some tumor entities GLO1 expression was associated with advanced tumor stages or drug resistance." (PMID 28549423, 2017). "On the other hand, GLO1 is overexpressed and/or amplified in tumours and its loss has been associated with MG-induced cytotoxicity and apoptosis." (PMID 28916747, 2017). "Growth arrest of tumor cells resulting from GLO1 inhibition was shown to be associated with elevated levels of MGO." (PMID 27999356, 2016). "As to GSTP1 and PON1 192 polymorphisms, the mutant Val and R alleles, respectively, were associated with a decreased risk of developing BC, while polymorphisms in PON1 55 and GLO1 were associated with an increased risk of this neoplasia." (PMID 19379515, 2009).